IL6 (interleukin 6)
Diseases named in the same sentence as IL6 in open-access papers (continued):
Sharing a sentence is not in itself a finding about the gene and the disease.
COVID-19 (continued). "They enrolled 149 COVID-19 positive patients and found that cardiac Troponin I levels were in significant correlation with ferritin levels, IL-6, IL-8 and high-sensitivity CRP." (PMID 34300181, 2021). "It has been shown that the serum metabolites involved in tryptophan and kynurenine metabolism correlate with IL-6 in COVID-19 patients." (PMID 33712622, 2021). "COVID-19 ARDS is triggered by a cytokine storm in which IL-6 plays a key role; thus, an anti-IL-6 receptor antibody showed favorable effects in patients with COVID-19 ARDS." (PMID 34530920, 2021). "Cytokine excess, in particular IL-2, IL-4, IL-6, TNF-α, and IFN-Ɣ are known drivers of the overactive inflammatory response and associated COVID-19 severity." (PMID 34675810, 2021). "Animal and clinical studies on SARS-CoV-2 have revealed that blockage of the transcription factor kappa-B (NF-κB) can reduce IL-6 expression, and can be a potential target to treat critically ill patients with COVID-19." (PMID 34066983, 2021). "Higher IL-6 levels are associated with reduced MWE, providing a possible pathophysiologic link between increased inflammation and adverse outcomes in COVID-19." (PMID 34195234, 2021). "A common clinical complication associated with COVID-19 is acute respiratory distress syndrome (ARDS) attributed to a cytokine storm of IL-1β, IL-6, IFN-γ, and TNF, among others." (PMID 34445140, 2021). "COVID-19 children had elevated levels of IFNγ, IL-2, TNFα, IL-1α, IFNα, IFNβ, IL-6, IL-17A and IL-10 in comparison to seropositive and/or control children." (PMID 33813138, 2021). "The main active ingredients of AE against COVID-19 were quercetin, kaempferol and luteolin, and the important targets were IL-6, MAPK1, MAPK8, IL-1β, and RELA." (PMID 33658066, 2021). "Innovative approaches for evaluating the biological activity of these cytokines in vivo are urgently needed to complement clinical trials of therapeutic targeting of IL-1β and IL-6 in COVID-19." (PMID 33319166, 2021). "Trials of immunomodulatory agents including those that inhibit the IL-6 pathway in COVID-19 patients are also underway, although initial results for one of these agents, tocilizumab, proved disappointing." (PMID 33493185, 2021). "It is thought that all these genes are either upregulated or predicted to be activated and would participate in the general increase of IL6 signaling and its unfortunate consequences in COVID-19." (PMID 33941085, 2021). "Overall, pronounced inhibition of TNFα and IL-6 is the most important finding, as these molecules are currently considered to be the key actionable targets in COVID-19 cytokine storm and ARDS." (PMID 33465050, 2021). "Elevated levels of interleukin 6 are characteristic of COVID-19 patients with poor outcomes and are one of the best laboratory indicators of respiratory failure and death." (PMID 34685427, 2021). "COVID-19 patients showed a profile of pro-inflammatory serum cytokines compared to controls, with higher levels of IL-2, IL-6, IL-15, and IP-10." (PMID 33718270, 2021). "The IL-6 levels in critical patients with COVID-19 were much higher than the levels set as the cut-off value for IL-6 detection, which meant that this group of patients still had a high level of inflammation." (PMID 33746945, 2021). "Second, a score for the Severe COVID-19 patients was defined as S2 = (IL-6+sCD40L/1000 + VEGF/10 + 10*IL-10)/(IL-2 + IL-8)." (PMID 34262570, 2021). "This coagulopathy appears to be a core pathophysiology of COVID-19 as rising D-dimer levels, correlate with a poor prognosis, as do rising levels of IL-6 and CRP." (PMID 33833683, 2021). "Patients presenting with severe manifestations related to COVID-19 were reported to have increased plasma concentrations of chemoattractant molecules and pro-inflammatory cytokines, including IL-10, IL-6, IL-1 and TNF-α." (PMID 33709775, 2021).
COVID-19 (continued). "NF-κB-derived high IL-6 levels are biomarkers of COVID-19 severity and predict mortality; IL-6 is thus a potential target for immunotherapy." (PMID 34630379, 2021). "COVID-19 patients have higher serum levels of IL-6, IL-1β, soluble IL-2 R, IL-8, IL-10, IL-17, and TNF-α." (PMID 33757410, 2021). "The IL-6 cytokine was correlated with the symptomology of COVID-19 patients, including pulmonary inflammation and excessive lung damage." (PMID 34372552, 2021). "In particular, compared with IL-6 levels in COVID-19 patients with normoglycemia, higher levels of IL-6 in patients with hyperglycemia or elevated blood sugar were observed on admission." (PMID 33480978, 2021). "The article has highlighted that the pathophysiology of the COVID-19 cannot be explained solely on the basis of the increase in a few inflammatory cytokines such as IL-6 and TNF." (PMID 34373466, 2021). "Mechanistically, COVID-19–related cytokines, such as IL-6, IL-17, and TNF-a, induce oxidative stress and inflammation in endothelial and vascular smooth muscle cells, promoting micro- and macro-vascular disease." (PMID 34151246, 2021). "Clinical trials are under evaluation to gain insights into the role of BTK inhibition in improving COVID-19 by reducing the levels and effects of IL-6." (PMID 34001144, 2021). "Recent published studies have reported that elevated inflammatory cytokine (such as TNFα, IL-1β, IL-6, IL-10, IL-17, IL-18, and IFNγ) levels were seen in active COVID-19 cases compared to healthy donors." (PMID 34348897, 2021). "Patients with severe and critical COVID-19 were characterized by higher levels of IL6, C-reactive protein and soluble IL2-receptor expression." (PMID 34869058, 2021). "Concentrations of several proinflammatory cytokines, including interleukin (IL)-6, are substantially increased in patients with severe COVID-19." (PMID 33918563, 2021). "Although other compounds were not as common as those four compounds above, given their favorable affinity with IL-6, they can potentially be effective drugs for COVID-19 treatment in the future." (PMID 33146673, 2021). "Often used to treat chronic inflammatory conditions such as rheumatoid arthritis, TCZ has become a pharmaceutical of interest for the treatment of COVID-19 because of the role IL-6 plays in this disease." (PMID 33688554, 2021). "The inflammatory biomarker IL-6 is an indicator of COVID-19 severity and tocilizumab has been employed in clinical trials for treating critically ill persons." (PMID 34287285, 2021). "IL-10/IL-6 is an index of the anti-inflammatory/pro-inflammatory balance which is severely disturbed in severe COVID-19, much more than in bacterial sepsis." (PMID 33682678, 2021). "When comparing sepsis with COVID-19 patients, serum IL-6 rates are typically five to 100 times higher in sepsis conditions than in patients with COVID-19." (PMID 34445700, 2021). "Patients with COVID-19 have increased plasma concentrations of IL-6, which significantly correlated with a reduced number of NK cells." (PMID 34603758, 2021). "The exaggerated hyperinflammatory response that occurs in severe COVID-19 patients, particularly the systemic elevation in IL-6, has been suggested to drive this relationship between disease severity and elevated neutrophil counts." (PMID 34149717, 2021). "In fact, the level of IL-6 was confirmed to be correlated with pulmonary infiltration areas of severe COVID-19 patients." (PMID 34987397, 2021). "Immunological signaling pathways (e.g. IL-1, IL-6, IL-8) were included as they describe broadly the impact of the inflammatory setting in COVID-19 patients." (PMID 33941085, 2021). "Enteric glial cells serve as antigen-presenting cells to the GALT, and their activation is characterized by IL-6 release, contributing to inflammation in COVID-19." (PMID 34512253, 2021). "Lymphocyte and platelet counts, as well as interleukin-6 levels, can predict mortality of COVID-19 and help clinicians evaluate patient outcomes." (PMID 34938342, 2021).
COVID-19 (continued). "Intriguingly, PD-L1-, ILT-3-, and IDO-1-expressing monocytic MDSC were the dominant producers of IL-6 and IL-10, which correlated with the increased inflammation and accumulation of regulatory B and T cell subsets in severe COVID-19 patients." (PMID 33692788, 2021). "Our study aimed to describe the association between circulating IL-6 levels and MAFLD at hospital admission with risk of severe COVID-19." (PMID 33763027, 2021). "For a more targeted approach IL-6 (receptor) antagonist have been suggested as an effective treatment for severe COVID-19." (PMID 34728658, 2021). "The marked elevation of serum cytokines, especially tumor necrosis factor-alpha, interleukin 17 (IL-17), interleukin 8 (IL-8) and interleukin 6 (IL-6), is seen in patients with COVID-19 who go through pneumonia and hypoxia." (PMID 34070725, 2021). "Dysregulated inflammation is a key factor in the development of severe COVID-19, as suggested by the high expression of IL-6 in COVID-19 patients, which has a key role in inflammatory cytokine storm." (PMID 34471088, 2021). "The core of the current trial was focused on assessing the level of the vitamin D (serum 25(OH)D concentration), IL-6, and the renal glomerular filtrate (eGFR) in COVID-19 disease and non-COVID-19 patients in both groups." (PMID 34576798, 2021). "It is well established that IL-6 is the proinflammatory cytokine that is found in highest levels in serum of severe COVID-19 patients." (PMID 33981312, 2021). "This includes for example therapeutic antibodies interfering with either IL1β, IL6, TNFα or their receptors directly contributing to the CRS associated with severe COVID-19." (PMID 34293006, 2021). "IL-6 increases the severity of COVID-19 by rearranging the angiotensin-converting enzyme (ACE2) receptors and inducing macrophage cathepsin L. Cathepsin L of macrophage cleaves the S1 subunit of the coronavirus spike glycoprotein." (PMID 34475485, 2021). "Cytokine secretion for Nano-curcumin-treated COVID-19 patients was reduced in comparison to placebo group (Paired T-test, p = 0.0082 for IL-1β and p = 0.0038 for IL-6)." (PMID 34443474, 2021). "In severely affected COVID-19 patients, however, excessive secretion of IL-6 and other pro-inflammatory cytokines summon T cell aggregation and cause T cell functional exhaustion with increased expression of PD-1 and NKG2A." (PMID 34001244, 2021). "IL-1 and IL-6 blocking therapies are more likely to provide survival advantage in hyper-inflamed COVID-19 patients when initiated before the establishment of severe respiratory failure." (PMID 33995419, 2021). "It demonstrated a close relationship between IL-6 levels and health conditions of patients with COVID-19." (PMID 33746945, 2021). "A study that enrolled 548 patients found that high cytokine levels (IL-2R, IL-6, IL-10, and TNF-α) were significantly associated with severe COVID-19 on admission, whose findings correspond with our results." (PMID 34489933, 2021). "Isolated circulating monocytes from acute COVID-19 patients showed a sustained production of IL-6 and tumor necrosis factor (TNF)-α." (PMID 34572439, 2021). "So far, adjunctive dexamethasone therapy has been shown to prevent mortality in severe COVID-19, while monoclonal antibodies against IL-6 showed ambiguous results in clinical trials [,20]." (PMID 34000622, 2021). "Biomarkers to distinguish disease progression in COVID-19 include interleukin (IL)-6, C-reactive protein (CRP), D-dimers and lactic dehydrogenase (LDH), yet our understanding of their role in disease pathophysiology remains limited." (PMID 34471264, 2021). "However, IL-6, IL-8, IL-10 and IP-10 showed either diagnostic and prognostic classification performance, with an AUC > 0.95 in at least 2 out of the 3 groups (Control vs mild + severe COVID-19; mild vs control + severe COVID-19; severe vs control + mild COVID-19)." (PMID 34675240, 2021).
COVID-19 (continued). "In the context of COVID-19 epidemic, other researchers found that the maximal level of plasma IL-6 was higher in critical cases than in severe cases (median 1072.98 pg/mL (IQR 453.85–9163.64) vs. 49.14 pg/mL (IQR 27.98–101.30); p = 0.001)." (PMID 34460840, 2021). "A high level of inflammatory cytokine (IL-6) was reported during early pandemic days in COVID-19 patients, with more than 80 pg/mL IL-6 levels, a good indicator of respiratory failure and death." (PMID 34458380, 2021). "It should be considered that high levels of IL-6 are related to a poorer prognosis of COVID-19 patients, mostly due to a much extent of respiratory involvement." (PMID 33765288, 2021). "Tocilizumab, an IL-6 pathway inhibitor, effectively reduces mortality of severely ill and lymphopenic COVID-19 patients, notably by attenuating inflammation and normalizing their circulating T cell rates." (PMID 34835019, 2021). "The effect of COVID-19 on the cardiovascular system is more severe in patients with elevated levels of inflammatory factors such as interleukin (IL)-6." (PMID 33995341, 2021). "The research investigated, for the first time, the efficacy of two different types of anti-inflammatories on patients with severe forms of COVID-19: the interleukin IL-1 inhibitor, called Anakinra, and the IL-6 inhibitors Tocilizumab and Sarilumab." (PMID 34072708, 2021). "Given the propensity for systemic IL-1β, TNFα, and IL-6 to contribute to peripheral and central neuronal sensitization, it can be hypothesized that the increased prevalence of neurological manifestations seen in severe COVID-19 may be associated with elevations of these cytokines." (PMID 33458558, 2021). "One of the characteristics of COVID-19 is the presence of elevated IL-6 serum levels and low IFN response." (PMID 33668085, 2021). "Further to this, the level of the cytokine storm modulator interleukin IL-6 has shown to be increased in more severe cases of COVID-19 compared to mild cases." (PMID 33969006, 2021). "The cytokine IL-6 was shown to be a valuable biomarker of COVID-19 severity and an indicator of viral load." (PMID 34578460, 2021). "Several therapeutic agents have been evaluated for treating COVID-19, such as the antiviral Remdesivir, steroids (e.g., dexamethasone and methyl-prednisone) and anti-IL-1 and anti-IL-6 inhibitors." (PMID 34677394, 2021). "Not only significantly elevated serum IL-6 levels were noted in patients with COVID-19, but predictivity of high IL-6 for poor outcomes in COVID-19 was also reported." (PMID 34803441, 2021). "Another key potential link between COVID-19 and hypertension is IL-6, a pleiotropic cytokine found at high levels in cytokine storms, which are responsible for stimulating the production of acute-phase proteins." (PMID 34441038, 2021). "Our research aimed to systematically investigate the active components of ‘three formulas and three medicines’ for COVID-19 treatment and the mechanism based on IL-6 integrating network pharmacological methods." (PMID 33146673, 2021). "This elevation in IL-6 plays a role in the induction of a severe systemic inflammatory response in patients with COVID-19, which leads to the consideration of targeted therapy against this inflammatory marker." (PMID 34177298, 2021). "Since its important role in SARS-CoV-2 induced cytokine release syndrome, the IL-6 signaling pathway has become a promising therapeutic target for severe forms of COVID-19." (PMID 34829920, 2021). "One hundred and thirty-nine (34.4%) received systemic corticosteroids, and 73 (18.1%) targeted COVID-19 treatment (anti-IL-6 drugs such as tocilizumab or eculizumab)." (PMID 34829210, 2021). "Further, the level of circulating Th cells capable of producing IL-6, GM-CSF, and IFNγ was reported to be significantly increased in patients with COVID-19, especially in patients with severe infection." (PMID 34696395, 2021).
COVID-19 (continued). "For inflammation indicators, including ESR, CRP and IL-6, COVID-19 all patients with COVID-19 infection showed a significantly elevated state (the IL-6 level in patients with mild cases was within the normal range)." (PMID 34222271, 2021). "Many cytokines in COVID-19 patients were significantly different from those in healthy individuals, including IL-2, IL-4, IL-6, CCL2, IFN-γ, and TNF-α." (PMID 34489974, 2021). "Based on the analysis of changes in IL-6 levels during the infection stage, the inflammation condition of patients with COVID-19 was uncovered, especially the condition near the day of discharge." (PMID 33746945, 2021). "This predictive model assembling severe COVID-19-related proteins supports a role for known contributors to the cytokine storm such as IL1β, IL6, TNFα, JAK2, but also less prominent actors such as IL17, IL23 and C5a." (PMID 34293006, 2021). "Unexpectedly, enhanced levels of bacterial DNA and LPS (probably of lung origin) can also be found in the plasma of COVID-19 patients, which were positive correlated with augmented release of IL-6 and other inflammatory mediators." (PMID 34945111, 2021). "Accordingly, several molecular measurements associated with systemic inflammation, namely, CRP, D-dimers, ferritin, and IL-6 were elevated in plasma from COVID-19 patients in our cohort." (PMID 35095880, 2021). "Lymphopenia and elevated proinflammatory cytokines have been reported to be frequent in severe cases of COVID-19 in comparison with milder cases, with higher serum concentrations of IL6, IL10, IL2 and IFN-γ present in severe cases." (PMID 33776561, 2021). "Michalakis and colleagues illustrated that activated NF-κB signaling pathway in COVID-19 triggers release of IL-6, aldosterone and vascular endothelial growth factor (VEGF) from adipose tissue in obese patients with subsequent development of hypertension." (PMID 34806090, 2021). "These factors explain the strong temporal correlations in severe COVID-19 patients observed between increases in the levels of IL-6, CRP, and D-dimer, and with lymphopenia and the development of progressive organ failure." (PMID 33550983, 2021). "The cytokine profile of HLH is characterized by high levels of IFN-γ, TNF-α, IL-6, IL-10, and IL-12, a similar pattern to what is found in severe COVID-19." (PMID 33557908, 2021). "The opposite behaviour of analysed markers of inflammatory and endothelial damage, IL-6 and sFlt-1, further evidences the significant role of inflammation and endothelial damage in determining the severity of COVID-19." (PMID 34620968, 2021). "Two independent studies reported that serum levels of ferritin and IL-6 are increased in patients with severe COVID-19 and decreased in recovered cases." (PMID 35126355, 2021). "Ovarian cancer is known to present increased levels of IL-2, IL-6, IL-12 and Il-13, while high levels of IL-6 are frequently encountered in COVID-19." (PMID 34063231, 2021). "Thiol concentrations decreased while IMA, IL-6, calprotectin and PSEP increased with disease severity in COVID-19 patients and were associated with increased O2 needs and ICU admission." (PMID 34299080, 2021). "Severe COVID-19 patients often present with high levels of inflammatory markers such as C-reactive protein, interleukin-2R (IL-2R), IL-6, IL-10, and tumor necrosis factor-α as well as symptoms of dyspnea." (PMID 34356969, 2021). "One of the first strategies toward treating the COVID-19 cytokine storm syndrome was targeting IL-6." (PMID 34575353, 2021). "Previous research has found a correlation between increases of interleukin 6 and kynurenine levels in COVID-19 patients compared to controls." (PMID 34928464, 2021). "Consistent with this, COVID-19 patients demonstrate up-regulated C-reactive protein level, the elevated level of interleukin 6 (IL-6), increased neutrophil counts, and decreased lymphocyte counts." (PMID 33806290, 2021).